MMP9 (matrix metallopeptidase 9)
Diseases named in the same sentence as MMP9 in open-access papers (continued):
Sharing a sentence is not in itself a finding about the gene and the disease.
leukemia (continued). "The CCK-8 results disclosed that DC-CIK cells effectively repressed the proliferation capacities of leukemia cells, and MMP9 or CCL1 knockdown in DC-CIK cells further prevented the proliferation of leukemia cells relative to that in the DC-CIKsh-NC group." (PMID 37200633, 2023). "DC-CIK cells with MMP9 and CCL1 knockout alone had little effect on leukemia cells, while knockdown of MMP9 and CCL1 in DC-CIK cells increased cytotoxicity, suppressed proliferation, and induced apoptosis of leukemia cells." (PMID 37200633, 2023). "It has been shown that PESV, an active ingredient of Buthus martensii Karsch, can effectively improve the expression of E-cadherin in leukemia mice and can interfere with the growth and metastasis of Lewis lung carcinomas in mice by inhibiting MMP-9." (PMID 35463079, 2022). "It has been shown that the ID1 transcriptional inhibitor-MMP9 axis can enhance the invasiveness of BCR-ABL1 transformed leukemia cells." (PMID 35111390, 2022). "EMT is the backbone for leukemia cells to become anoikis resistant, which is attained by enhancing MMP-9 and IL-8, playing an integrative role in the proliferation of leukemia cells." (PMID 35815090, 2022). "Consistently, matrix metalloproteinase-9 (MMP-9) produced by leukemia cells facilitated tumor progression via remodeling of the ECM of the BM microenvironment." (PMID 33330442, 2020). "We performed a secondary transplantation and observed a significant reduction of leukemia load in the peripheral blood of secondary recipient mice transplanted with BM from MMP-9 inhibitor-treated primary B-ALL mice compared with controls (P = 0.03)." (PMID 31919471, 2020). "In summary, our data suggest that a proinflammatory state is created in the leukemic BMM in B-ALL by the release of Tnfα, which leads to remodeling of the BMM, breakdown of the ECM, and increased invasion of leukemia cells via the secretion of MMP-9 from MSC." (PMID 31919471, 2020). "In summary, leukemia cell-derived Tnfα induced MMP-9-expression by the BMM promoting B-ALL progression." (PMID 31919471, 2020). "In a large proportion of B-ALL cases, leukemia cell-specific production of MMP-9 has been shown, as also described in the BloodSPot Database and found to a low extent in our study." (PMID 31919471, 2020). "AMSA is known to suppress MMP-2 and MMP-9 expression in human leukemia cells via reactive oxygen species (ROS) generation." (PMID 31848363, 2019). "It has been demonstrated that the up-regulated expression of matrix metalloproteinase (MMP) 2/MMP-9, as a metastasis biomarker, can fortify the metastatic potential of leukemia." (PMID 29883990, 2019). "Members of the matrix metalloproteinase family have been implicated in the migration and invasion of leukemia cell (MMP-2), and previously shown to mediate megakaryocyte transendothelial migration and proplatelet formation (MMP-9)." (PMID 29420626, 2018). "A previous study demonstrated that FN-mediated cell adhesion is required for the induction of MMP-2 and MMP-9 in human leukemia cells." (PMID 29706869, 2018). "In myeloid leukemia cell lines, Rap1GAP promotes leukemia cell differentiation and apoptosis, but increases leukemia cell invasion in vitro by the upregulation of MMP9." (PMID 28009991, 2017). "In leukemia B cells, we found that Wnt5a could upregulate MMP-9 expression via ROR1-dependent activation of NF-κB." (PMID 40295829, 2025). "In concordance with our results, MMP-9 may correlate with poor prognosis in leukemia and act as a potential prognostic biomarker." (PMID 40427122, 2025). "We examined the leukemia cells derived from TCL1 Tg or ROR1xTCL1 dTg mice for mouse MMP-9." (PMID 40295829, 2025). "A higher MMP-9 secretion was related to a lower overall survival (OS) rate in pediatric leukemia." (PMID 40427122, 2025).
leukemia (continued). "Furthermore, the expression of most M2-associated genes, such as Arg1, CCL3, CCL17, CD206, IL-10, and TGF-β decreases with the infiltration of leukemia cells, whereas the expression of MMP9 and VEGFα increases in the advanced stages of leukemia." (PMID 38779660, 2024). "The molecular consequences of the Ph chromosome form the BCR-ABL oncogene that encodes a chimeric BCR-ABL oncoprotein, which disrupts several factors (leptin, IL-8, MMP-9, and survivin) and pathways (Ikaros/Notch/CD-11d signaling pathways) responsible for the pathogenesis of leukemia." (PMID 35815090, 2022). "Similarly, IL-7-mediated signaling contributes to leukemia development and cancer cells typically have increased production of proteases such as MMP-9 and other MMPs." (PMID 34276694, 2021). "There was also evidence showing that TNF induced MMP9 expression or secretion in leukemia cells." (PMID 33109189, 2020). "Its expression may be increased in cancer cells of solid tumors, where it may correlate with metastasis, while in chronic lymphocytic leukemia (CLL) leukemia-cell specific, increased expression of MMP-9 contributes to disease progression." (PMID 31919471, 2020). "Because ABL allosteric inhibitors are currently in clinical trials for the treatment of therapy-resistant leukemia patients, these inhibitors could be employed to impair MMP9 secretion and function in metastatic lung adenocarcinoma cells primed by MSCs." (PMID 33119681, 2020). "MMP-2 and MMP-9 have been associated with degradation of endothelial tight junction proteins, permeabilization of the blood-brain-barrier (BBB) and subsequent brain colonization in mouse models of leukemia." (PMID 25668816, 2015). "Notably, this study showed that EZH2 inhibitor (DZNep) increased the levels of MMP9 in leukemia cells." (PMID 25955299, 2015). "The deregulated expression of pro-MMP-9 is observed in leukaemias." (PMID 24713998, 2014). "Besides, GLY also decreased the expression level of p-FAK, p-Akt, p-ERK, p-Rb, MMP-2, and MMP-9 whereas increased p21 expression to attenuate leukemia cell growth and migration." (PMID 23573143, 2013). "Hypothesizing that leukemias may instruct the BMM to degrade the ECM, we show, that MMP-9-deficiency in the BMM prolongs survival of mice with BCR-ABL1-induced B-cell acute lymphoblastic leukemia (B-ALL) compared with controls and reduces leukemia-initiating cells." (PMID 31919471, 2020). "We next examined whether CD82-induced EZH2 repressed the levels of MMP9 in leukemia cells." (PMID 25955299, 2015). "Compared with the DC-CIKsh-NC group, DC-CIK cells after the knockdown of MMP9 or/and CCL1 significantly promoted the apoptosis of leukemia cells." (PMID 37200633, 2023). "Due to the promotion of MMP9- and CCL1-silenced DC-CIK cells on the T-cell activation, we further verified the effect of coculture of T cells with leukemia cells on leukemia cell proliferation and apoptosis." (PMID 37200633, 2023). "In macrophages, eNAMPT promotes cell survival upon ER stress, up-regulates MMP-9 and MMP-2, and is able to induce the M2-polarization of macrophages in leukemia." (PMID 36674688, 2023). "To investigate the function of MMP9 and ABCG2 in human leukemia cells, we overexpressed these two genes in the NB4 cells." (PMID 34093860, 2021). "In agreement with our study autocrine secretion of Tnfα has been shown to support and maintain leukemia cells in CML, and Tnfα treatment of leukemia cells is known to lead to NFκB-mediated transcription of MMP-9." (PMID 31919471, 2020). "Matrix metalloproteinase-9 (MMP-9), secreted by leukemia cells, facilitates tumor progression via remodeling of the extracellular matrix (ECM) of the BMM." (PMID 31919471, 2020). "AML biomarkers NPM1, FLT3, CXCR4, MMP9 and IGF-IR are also present in AML cell derived exosomes, along with mRNAs involved in leukemia development." (PMID 27191983, 2016).
leukemia (continued). "In this review, we summarize the current literature on the expression profiles of pro-MMP-9 and NGAL as prognostic factors in leukaemias." (PMID 24713998, 2014). "Recently, we suggested a potential role of MMP-9, MT1-MMP, TIMP-1, TIMP-2 and VEGF in the pathogenesis of canine leukaemia." (PMID 23641796, 2013). "We also examined for differences in MMP-9 expression by leukemia cells with or without ROR1 in murine leukemia models." (PMID 40295829, 2025). "Similarly, the results from EdU staining also testified that MMP9- and CCL1-silenced DC-CIK cells displayed the same inhibitory effects on the proliferation of the cocultured leukemia cells with activated T cells." (PMID 37200633, 2023). "Next, to investigate whether MMP9- and CCL1-silenced DC-CIK cells can significantly affect the proliferation and apoptosis of leukemia cells, MMP9- or/and CCL1-silenced DC-CIK cells were cocultured with 3 leukemia cell lines." (PMID 37200633, 2023). "We also demonstrated that overexpression of MMP9 and ABCG2 in the leukemia cell line could induce apoptosis and differentiation, indicating that these two genes could be potential targets for AML therapy." (PMID 34093860, 2021). "Most previous reports on the role of MMP-9 in cancer have focused on the cancer cell-specific production and release of MMP-9 leading to increased invasion and progression, both in solid tumors, as well as in leukemia." (PMID 31919471, 2020). "Co-cultures of BMSCs and leukemia cells could time-dependently stimulate the secretion of uPA, uPAR, PAI-1, MMP-9, and VEGF-A, indicating that uPA system plays an important role in the BMM." (PMID 33146708, 2020). "Moreover, we explored the expression of uPA, uPAR, PAI-1, MMP-9, and VEGF-A under co-culture conditions and the effect of the uPA system on the BMM during leukemia." (PMID 33146708, 2020). "Our results further suggest that MMP-9 inhibition may represent a feasible adjunct treatment strategy in B-ALL, where leukemia relapse and progression remain major concerns." (PMID 31919471, 2020). "Apart from MMP-9, the involvement of these proteases in leukemia progression had not been investigated." (PMID 27802179, 2016). "This review is aimed at (i) providing an overview of the current literature on the expression profiles of pro-MMP-9, NGAL and their complex in leukaemias and (ii) highlighting the recent advances in understanding the roles of (pro)-MMP-9, NGAL and pro-MMP-9/NGAL in cancer including leukaemia." (PMID 24713998, 2014). "Emerging knowledge about the coexpression and the biology of (pro)-MMP-9, NGAL and their complex in cancer including leukaemia may improve treatment outcomes." (PMID 24713998, 2014). "CLL cells recirculate between blood and lymphoid tissue compartments, and such trafficking requires leukemia cells to pass through endothelial barriers and transverse the extracellular matrix (EM), a process that is facilitated by matrix metallopeptidases (MMP), such as MMP-9." (PMID 40295829, 2025). "Likewise, the EdU staining results also manifested that the proliferation of leukemia cells could be notably suppressed by DC-CIK cells, after MMP9 or/and CCL1 silencing." (PMID 37200633, 2023). "Besides, we also uncovered that the cosilencing DC-CIK cells of MMP9 and CCL1 could further enhance the inhibitory effects of MMP9 or CCL1 knockdown on the proliferation of leukemia cells." (PMID 37200633, 2023). "Similarly, exosomes carry Fas ligand (FAS-L), NPM1, FLT3, matrix metallopeptidase 9 (MMP9), insulin-like growth factor type 1 receptor (IGF1-R), CXCR4, and chaperones to alter the BM microenvironment and to improve the survival of leukemia cells, especially LSCs." (PMID 35865470, 2022). "While the knockdown of Tnfα in leukemia cells in our study prolonged the survival of mice with B-ALL by a concomitant reduction in MMP-9 production by the BMM, the impairment of autocrine, leukemia-promoting secretion of Tnfα, as shown in CML, may be contributory." (PMID 31919471, 2020).
leukemia (continued). "However, as demonstrated in our data, leukemia cell-specific production of MMP-9 does not influence survival, suggesting that the Tnfα-induced production of MMP-9 by MSC and possibly other niche cells plays a more prominent role." (PMID 31919471, 2020). "Thus, blockade of CD82 might augment the levels of MMP9 and CXCR4, resulting in mobilization of leukemia cells into the peripheral circulation." (PMID 26139471, 2015). "This may explain the abnormal expression of pro-MMP-9 and NGAL in leukaemias." (PMID 24713998, 2014).
neuroblastoma (54 papers, 2002 to 2025). Neuroblastoma (NB) is the most common solid, extracranial childhood tumor. "When neuroblastoma tumor cells were implanted into MMP-9-deficient mice, the tumor vasculature appeared to be inhibited." (PMID 26729169, 2015). "This suggests possible involvement of factors other than CXCL12 in the increased MMP-9 secretion and invasiveness associated with neuroblastoma cells in the presence of MSC secretome." (PMID 25774696, 2015). "Gelatinase B/MMP-9 is also induced in neuroblastoma cells in association with spontaneous epithelial to neuroblast phenotype conversion and following treatment with all-trans-retinoic acid and released from IL-8 stimulated neutrophils." (PMID 24473089, 2014). "Its down-regulation due to direct inhibition by miR-15a leads to increased secretion of MMP9 in neuroblastoma cells." (PMID 40481348, 2025). "MMP-9 was also shown to be expressed in neuroblastoma tissue, with 94% of specimens testing positive for MMP-9." (PMID 40426729, 2025). "It has also been shown to inhibit MMP-2 and MMP-9 in SK-N-BE human neuroblastoma and HT1080 human fibrosarcoma cells." (PMID 38611849, 2024). "This combination also activated the wnt/β-catenin pathway; however ALK cleavage by MMP-9 in neuroblastoma results in β-catenin release from ALK." (PMID 38397899, 2024). "The effect of nordentatin on MMP-9 expression and its implications in neuroblastoma migration and invasion were investigated." (PMID 35723293, 2022). "In turn, the secretome of bone marrow MSCs was shown to promote the expression of the 47 kDa CXCR4 isoform and also increased MMP-9 secretion, expression of integrin α3 and integrin β1, supporting the invasive potential of neuroblastoma cells." (PMID 34831167, 2021). "Since MMP-9 is generally secreted in negligible quantities by neuroblastoma cell lines, including SH-SY5Y cells, it was possible to observe and quantify the effect of POE mainly only on the activity of MMP-2 secreted in the culture medium." (PMID 34677478, 2021). "Numerous studies have implicated that MMP-9 and MMP-2 are involved in invasive, metastatic, and poor prognosis of various cancers, including neuroblastoma." (PMID 30862004, 2019). "A significant reduction in the levels of secreted MMP-9, compared to control levels, was observed in neuroblastoma cell lines treated either with AMD 3100 or with anti-47 kDa CXCR4 neutralizing antibody." (PMID 25774696, 2015). "Pre-treatment with mRPMI increased the levels of secreted MMP-9 compared to the control (serum-starved) neuroblastoma cells." (PMID 25774696, 2015). "This group also discovered that neuroblastomas with unfavorable histology and advanced disease have more inflammatory cells expressing MMP-9." (PMID 26729169, 2015). "In this connection, we found that 24-OH and 27-OH, but also 7β-OH, induced expression of IL-8, MCP-1, β1-integrin, CD36, and MMP-9 in human neuroblastoma SH-SY5Y cells." (PMID 24802026, 2014). "The RBE element (−54) also functions together with the NF-κB element (−600) in gelatinase B/MMP-9 transcription induced by spontaneous epithelial to neuroblast conversion exhibited by SK-N-SH neuroblastoma cells." (PMID 24473089, 2014). "The expression of MMP-9 by stromal cells has previously been shown to regulate the vascular architecture in a murine orthotopic MYCN-amplified neuroblastoma xenograft model by promoting pericyte recruitment." (PMID 24667968, 2014). "Stromal MMP-9 regulates the vascular architecture in neuroblastoma by promoting pericyte recruitment." (PMID 21876694, 2012). "Combination of TSA and IFN-α not only decreased endothelial cell migration, invasion, and capillary tubule formation but also inhibited expression of VEGF, HIF-1α, and MMP-9 in neuroblastoma cells." (PMID 21876694, 2012).
neuroblastoma (continued). "PEGylated SN38 (EZN-2208), a novel topoisomerase I inhibitor, showed promising anti-neuroblastoma efficacy through increasing apoptosis and reducing expression of VEGF, MMP-2, and MMP-9 in preclinical in vitro and in vivo models of human neuroblastoma." (PMID 21876694, 2012). "Previous studies have found that neoplastic cells can express factors that stimulate MMP secretion by stromal cells and further work is needed to determine whether P-Rex1 expression affects MMP-9 secretion by stromal cells in neuroblastoma." (PMID 38884093, 2024). "Furthermore, Sbai and colleagues showed that the intracellular transport of MMP9 in neuroblastoma cells was partly dependent on the dynein/dynactin molecular motor." (PMID 34071761, 2021). "Moreover, galangin reduces MMP-9 expression and cell migration in human neuroblastoma cell lines and human fibrosarcoma cells (Choi, Lee & Lee, 2015)." (PMID 34589307, 2021). "Therefore, we attempted to explore the molecular mechanisms by which galangin inhibited MMP-9 expression and cell migration induced by thrombin in SK-N-SH cells (a human neuroblastoma cell line)." (PMID 30562971, 2018). "Reduced integrin α3 β1 expression, could be directly related to reduced MMP-9 secretion and lower invasiveness of neuroblastoma cells, under conditions of CXCR4 blockage." (PMID 25774696, 2015). "A role for matrix metalloproteinase-9 (MMP-9) has been described in neuroblastoma." (PMID 26729169, 2015). "In human neuroblastoma cells, spontaneous EMT-like phenotypic conversion from a less invasive epithelial to more invasive neuroblast phenotype, associates with the induction of gelatinase B/MMP-9 expression and increased gelatinase B/MMP-9-mediated invasion." (PMID 24473089, 2014). "Increased expression of both MMP-2 and MMP-9 is also evident from studies in two neuroblastoma cell lines (LAN-5 and GL-LI-N) and immunohistochemical analysis of tissue biopsies of human neuroblastoma indicating that expression of these MMPs is correlated with angiogenesis in advanced stages." (PMID 21876694, 2012). "Therefore, inhibition of MMP-2 and MMP-9 has great potential in the treatment of neuroblastoma." (PMID 30862004, 2019). "To consider the possibility that meningothelial cells may be a source of IGFBP-cleaving proteases, we performed western blotting of MMP9 and tPA on cultured BMEN and HMC cells, using cultured human neuroblastoma (MC65) cells as a positive control for MMP9 expression." (PMID 27255663, 2016). "Ribatti and co-workers studied neuroblastoma tumor samples using immunohistochemical staining to determine the expression of MMP-2 and MMP-9." (PMID 32751899, 2020). "Here, we also found that downregulation of Prp19 inhibited invasion and migration of neuroblastoma cells and reversed EMT with an upregulation of E-cadherin and downregulation of MMP9, and overexpression of Prp19 had the opposite results." (PMID 33224878, 2020). "In human neuroblastoma SH-SY5Y cells, BDE-47 had limited cytotoxicity but significantly increased the in vitro cell migration and invasion by up-regulating MMP-9 through the GPR30/PI3K/Akt signaling pathway." (PMID 31737560, 2019). "Conversely, obstructing matrix metallopeptidase 9 (MMP-9) could impede ALK cleavage, reducing migration and invasion of neuroblastoma cells, hinting at a promising therapeutic approach." (PMID 38397899, 2024). "Human neuroblastoma tumors xenotransplanted in MMP-9 (+/+) and MMP-9 (−/−) mice showed that bone marrow-derived MMP-9 regulates the recruitment of leukocytes and endothelial cells along with pericytes from bone marrow into tumor stoma leading to neovascularization and tumor progression." (PMID 21876694, 2012). "MMP-9 is not expressed in neuroblastoma cell lines, but it is present in both inactive and active forms in tumor tissues." (PMID 21876694, 2012).